IKZF1 (IKAROS family zinc finger 1)
Diseases named in the same sentence as IKZF1 in open-access papers (continued):
Sharing a sentence is not in itself a finding about the gene and the disease.
immune thrombocytopenia (4 papers, 2019 to 2024). "We report a novel variant in IKZF1 associated with IKAROS haploinsufficiency in a patient with familial immune thrombocytopenia (ITP)." (PMID 31069201, 2019). "The herein described patients all carry germline IKZF1 variants with functional HI and have a history of recurrent bacterial or viral infections, immune thrombocytopenia and inflammatory signs like arthritis and eczema, but no history of malignant disease." (PMID 38813543, 2024). "Interestingly, individuals with IKZF1 haploinsufficiency manifest immune thrombocytopenia (ITP)." (PMID 37162944, 2023).
inflammatory bowel disease (4 papers, 2017 to 2025). A spectrum of small and large bowel inflammatory diseases of unknown etiology. "The trans-eQTLs contributing to this association with GATE scores for ISGs include IFIH1, IKZF1, and CARD9, previously reported as GWAS hits for inflammatory bowel disease." (PMID 40996888, 2025). "Herein we describe 11 patients with heterozygous IKZF1 variants from eight different families with autosomal dominant CVID and two siblings with an IKZF1 variant presenting with inflammatory bowel disease (IBD)." (PMID 31057532, 2019). "In addition, we describe two siblings with inflammatory bowel disease (IBD) carrying an IKZF1 variant." (PMID 31057532, 2019).
lung carcinoma (4 papers, 2017 to 2022). "In the lung cancer, SIOMICS identified five shared motifs, which were similar to motifs of ZNF219, PATZ1 (MAZR), SP1, IKZF1 (Lyf-1), and the CAC-binding protein, respectively." (PMID 28684851, 2017). "In addition, patients with mRNA IKZF1 high expression had a better prognosis in TCGA LUAD, TCGA lung cancer, GSE37745, GSE37745, and GSE30219 cohorts (P < 0.05)." (PMID 34408984, 2021).
lymphoid leukemia (4 papers, 2012 to 2025). A malignant lymphocytic neoplasm of B-cell or T-cell lineage involving primarily the bone marrow and the peripheral blood. "Genetic variations of certain alleles of the IKZF1 gene and its family members are associated with the development of either type-1 diabetes or lymphoid leukemia." (PMID 41514592, 2025).
non-Hodgkin lymphoma (4 papers, 2023 to 2025). Distinct from Hodgkin lymphoma both morphologically and biologically, non-Hodgkin lymphoma (NHL) is characterized by the absence of Reed-Sternberg cells, can occur at any age, and usually presents as a localized or generalized lymphadenopathy associated with fever and weight loss. "CFT7455, a next-generation IKZF1/3 degrader with favorable pharmacological properties in models of MM, has promoted its inclusion in a phase 1/2 study in relapsed/refractory (R/R) MM and Non-Hodgkin Lymphoma (NHL)." (PMID 41050081, 2025).
B cell deficiency (3 papers, 2021 to 2023). A broad classification of disorders where circulating numbers of B lymphocytes are decreased or ineffective. "Although B cell deficiency is the most common immunological feature in patients with IKZF1 mutations, normal to high B cell numbers were observed in three of the family members, while they were low in the fourth (A.I.1)." (PMID 34694366, 2021).
colon cancer (3 papers, 2020 to 2022). "Through further experimental verification, we revealed that the expression of LCP1, ITGB2, and IKZF1 were significantly upregulated in right-sided colon cancer samples compared to that of left-sided colon cancer samples (p < 0.05)." (PMID 36230637, 2022). "Colon cancer outcomes are associated with changes in MDSC infiltration, and therefore LCP1, ITGB2, and IKZF1 may be novel targets for immunotherapy." (PMID 36230637, 2022). "As shown in the interaction network, immune-related gene PLCG2 and IGF1, which are up-regulated in colon tumor samples, have significantly strong correlation with several TFs: FOXP3, IKZF1, CBX7, LMO2, MEF2C, EPAS1 and MAF." (PMID 33996273, 2021).
lymphoid neoplasm (3 papers, 2023 to 2025). A neoplasm composed of a lymphocytic cell population which is usually malignant (clonal) by molecular genetic and/or immunophenotypic analysis. "The existence of loss of function or dominant negative IKZF1 somatic mutations in high-risk B-ALL highlights IKAROS as an essential lymphoid tumor suppressor." (PMID 40925926, 2025). "These additional findings included novel gene fusions and high-risk cytogenetic aberrations such as chromoanagenesis and IKZF1 loss, and the latter has a clinical implication in disease progression, prognosis prediction, and modification of therapy regimens in both myeloid and lymphoid neoplasm." (PMID 39596557, 2024).
prostate carcinoma (3 papers, 2021 to 2025). A carcinoma that arises from epithelial cells of the prostate gland. "We conducted a Spearman correlation analysis and found that RIOX2 expression was strongly correlated with ZNF143 expression while moderately with IKZF1 expression in prostate cancers." (PMID 36776320, 2023). "In solid tumors, including prostate cancer, lack of IKZF1 expression has been implicated as a mechanism for tumor immune evasion." (PMID 40428397, 2025).
thymic lymphoma (3 papers, 2022 to 2023). "On the other hand, we did not unequivocally establish the cause of the observed high frequency of Ikzf1 abnormalities with regard to the development of radiation-induced thymic lymphomas." (PMID 35336821, 2022). "On the other hand, the frequency of mutations in the Pten and Ikzf1 genes was similar in the thymic lymphomas induced after a single irradiation at infancy." (PMID 35336821, 2022). "Several mouse models with constitutive or conditional IKZF1 knockout exhibited disturbance of normal lymphoid and myeloid differentiation, and developed aggressive diseases such as widespread haematopoiesis failure, thymic lymphoma or T‐cell malignancies." (PMID 37345307, 2023).
viral infections (3 papers, 2018 to 2025). "At the same time, certain monogenic causes of the CVID phenotype (e.g., NFKB1, NFKB2, TNFSF12/TWEAK/, TNFRSF13B/TACI/, or IKZF1/IKAROS/) have been reported to cause severe viral infections individually." (PMID 41229388, 2025).
Arthritis (2 papers, 2019 to 2024). Inflammation of a joint. "The first truncating IKZF1 mutation associated with IKAROS haploinsufficiency was reported by Bogaert and colleagues in two siblings with different kinds of arthritis and recurrent bacterial sinopulmonary infections." (PMID 31057532, 2019).
asthma (2 papers, 2015 to 2018). "Of these, five missense mutations (one each in FAM134B, NPC1L1, IKZF1, SLC26A3 and GSDMB) showed evidence of association with asthma in the combined sample, two of which (IKZF1 and SLC26A3) were more significant in the African ancestry sample." (PMID 25591454, 2015).
B cell lymphopenia (2 papers, 2025). "Dominant-negative or biallelic nonsense variants in TCF3, encoding E12 and E47, as well as heterozygous deleterious variants in IKZF1, encoding IKAROS, lead to severe B cell lymphopenia." (PMID 41607487, 2025).
Burkitt lymphoma (2 papers, 2021 to 2022). A rare form of malignant mature B-cell non-Hodgkin lymphoma. "A heterozygous R502L mutation in IKZF1 gene was identified in P25, who came to our attention for Burkitt lymphoma, and subsequently developed AIN and ITP." (PMID 35058929, 2021). "In contrast to Burkitt lymphoma (BL), where MYC is almost exclusively fused to an immunoglobulin locus, up to 50% of MYC translocations in DLBCL involve non-immunoglobulin genes, including among others BCL6, PAX5, and IKZF1." (PMID 35060000, 2022).
colitis (2 papers, 2022 to 2023). Inflammation of the colon. "Although the number of participants with IBD or colitis was small, there was only one positive result from the IKZF1/SEPT9 assay (13%)." (PMID 37755164, 2023). "CNVs on IKZF1, FAN1 and IL1RN were linked to IRAE, colitis, hepatitis or pancreatitis." (PMID 35053465, 2022).
DiGeorge syndrome (2 papers, 2020 to 2021). "DiGeorge syndrome (del22q11) was most common, followed by mutations in CTLA4, RMRP, IKZF1, and KMT2D." (PMID 33968040, 2021).
lupus nephritis (2 papers, 2022 to 2026). Glomerulonephritis in the context of systemic lupus erythematosus. "This included IKZF1 (encoding IKAROS), a genetic susceptibility locus for human SLE and lupus nephritis." (PMID 36345939, 2022).
mantle cell lymphoma (2 papers, 2022 to 2025). Mantle cell lymphoma is a rare form of malignant non-Hodgkin lymphoma affecting B lymphocytes in the lymph nodes in a region called the ``mantle zone''. "have developed Ikaros (IKZF1) and Aiolos (IKZF3) as imide-based CDK4/6 degraders in mantle cell lymphoma cell lines." (PMID 36059670, 2022). "These PROTACs also targeted Ikaros (IKZF1) and Aiolos (IKZF3) and showed enhanced antiproliferative effects in mantle cell lymphoma (MCL) cell lines when both CDK4/6 and IKZF1/3 were degraded simultaneously." (PMID 40793752, 2025).
osteosarcoma (2 papers, 2017 to 2019). A usually aggressive malignant bone-forming mesenchymal neoplasm, predominantly affecting adolescents and young adults. "This is notable because IKZF1 is the top ranked gene at the Irish Wolfhound chr18:1 Mb osteosarcoma risk locus and is one of the top contributors to risk in the modeling studies." (PMID 30890123, 2019). "Runx1 and Ikzf1 have been shown to be targets of mirn23a miRNAs in hematopoietic cells, and Satb1 was shown to be a direct target in osteosarcoma cells." (PMID 28704388, 2017).
ovarian carcinoma (2 papers, 2019 to 2025). A malignant neoplasm originating from the surface ovarian epithelium. "IKZF1 expression was significantly associated with advanced stage and distant metastasis in ovarian cancer patients." (PMID 30816208, 2019).
psoriasis (2 papers, 2018 to 2019). An autoimmune condition characterized by red, well-delineated plaques with silvery scales that are usually on the extensor surfaces and scalp. "IKZF1 has been suggested to affect the STAT4 and IFN pathways, both of which involve in the pathogenesis of psoriasis." (PMID 29715312, 2018). "Further studies are worth to validate rs79824801 in an independent sample, to quantify the binding affinity of IKZF1 at this site, and to evaluate the consequence of IFN signaling in the biological mechanism of psoriasis." (PMID 29715312, 2018).
Alzheimer disease (1 paper, 2024). A progressive, neurodegenerative disease characterized by loss of function and death of nerve cells in several areas of the brain leading to loss of cognitive function such as memory and language. "Genes that were both selective for and highly expressed in the microglial cluster were Tgfbr1, Cyth4, Ikzf1, Dock2, and Inpp5d, many of which are associated with Alzheimer’s Disease (AD)." (PMID 38263132, 2024).
atherosclerosis (1 paper, 2025). A disease characterized by the build-up of fatty material and calcium deposition in the arterial wall resulting in partial or complete occlusion of the arterial lumen. "We identified 12 lactylation-related genes that are more reliably associated with atherosclerosis: five upregulated genes (LSP1, IKZF1, MNDA, RCC2, and WAS) and seven downregulated genes (CSRP2, PPP1CB, CSRP1, HEXIM1, CALD1, PDLIM1, and RANBP2)." (PMID 40248193, 2025).
autism (1 paper, 2018). Persistent deficits in social interaction and communication and interaction as well as a markedly restricted repertoire of activity and interest as well as repetitive patterns of behavior. "Overall, for the first time, we show that VAC pretreatment in early gestation is sufficient to prevent impairments in social interaction and lamination in an MIA-induced autism model and that this process is associated with neuronal differentiation and Ikzf1 gene." (PMID 30103815, 2018). "Taken together, our data provide evidence for the crucial role of Ikzf1 in determining cortical lamination and the development of autism-like behaviors in the late stage of prenatal development." (PMID 30103815, 2018). "Finally, RNA-Seq was carried out to explain the biological mechanism at the genome level, and Ikzf1 (IKAROS family zinc-finger 1) was proved to be tightly correlated with autism-like behavior through its regulation of neuronal differentiation." (PMID 30103815, 2018). "Consistently, our data showed that LPS mice had higher Ikzf1 expression than controls at a late stage (E18.5) and that VAC preconditioning rescued its expression (p < 0.05), supporting a vital role for Ikzf1 in the effect of VAC pretreatment on abnormal lamination and autism-like behaviors." (PMID 30103815, 2018).
bladder cancer (1 paper, 2022). "The network analysis revealed that GNAQ, NTRK3, and IKZF1 are related to UC because they are involved in PI3K/AKT and bladder cancer signaling." (PMID 35864526, 2022).
CNS lymphoma (1 paper, 2019). "However, mutations in IKZF1 have not been reported to be associated with human CNS lymphoma." (PMID 31057532, 2019).
COVID-19 (1 paper, 2022). A disease caused by infection with severe acute respiratory syndrome coronavirus 2. "Therefore, we present for the first time a case of CVID associated with a de novo heterozygous R162Q variant in the IKZF1 gene in a patient with a low humoral immune response to the complete COVID-19 vaccination program." (PMID 35566429, 2022). "Therefore, we present for the first time a case of CVID associated with a de novo heterozygous R162Q variant in the IKZF1 gene in a patient with a low antibody immune response and a positive cellular response to the complete COVID-19 vaccination program." (PMID 35566429, 2022).
dendritic cell neoplasms (1 paper, 2022). "Interestingly, IKZF1-alterations have been recently identified in patients with blastic plasmocytoid dendritic cell neoplasms, a rare hematological disease associated with cutaneous and solid organ infiltration and poor prognosis." (PMID 35562747, 2022).
dermatitis (1 paper, 2021). An inflammatory process affecting the skin. "We reported that IKZF1 transgenic mice developed spontaneous mucocutaneous inflammations such as ocular surface- and oral inflammation and dermatitis." (PMID 34926478, 2021).
diffuse large B-cell lymphoma (1 paper, 2020). "CC-122 binds CRL4CRBN E3 ligase to induce the degradation of IKZF1 and IKZF3 in MM cells, diffuse large B-cell lymphoma (DLBCL) cells and xenograft mouse models established from DLBCL cells." (PMID 31938543, 2020).
experimental autoimmune encephalomyelitis (1 paper, 2025). An autoimmune demyelinating disease of the central nervous system that is produced experimentally in animals by the injection of homogenized brain or spinal cord in Freund's adjuvant. "CD16+ monocytes showed downregulation of select transcription factor genes (RXRA, IKZF1, KLF4, IRF4) and CD81, a marker that facilitates monocytes homing to the CNS in experimental autoimmune encephalomyelitis (EAE)." (PMID 40067358, 2025).
head and neck squamous cell carcinoma (1 paper, 2024). A squamous cell carcinoma that arises from any of the following anatomic sites: lip and oral cavity, nasal cavity, paranasal sinuses, pharynx, larynx, and salivary glands. "IKZF1 is involved in lymphoid differentiation and its co-expression with SASH3 and IL10RA is associated with good prognosis of head and neck squamous cell carcinoma." (PMID 39107857, 2024).
IgG4-related disease (1 paper, 2024). "In familial IgG4-related disease, IKZF1 and UBR4 gene variants break T cell tolerance and concomitantly induce a Th2 response." (PMID 38885295, 2024).
inflammatory skin disease (1 paper, 2023). Inflammatory skin disorders covers a broad category that includes many conditions ranging in severity, from mild itching to grave medical health complications These disorders are common in people of all ages and races. "IKZF1 is a potential therapeutic target for several inflammatory skin diseases." (PMID 38014119, 2023).
Intellectual disability (1 paper, 2021). "Interestingly, syndromes caused by deletions of IKZF1 present with intellectual disability." (PMID 33786950, 2021).
lung adenocarcinoma (1 paper, 2025). A carcinoma that arises from the lung and is characterized by the presence of malignant glandular epithelial cells. "Furthermore, we analyzed the expression of RUNX3, IKZF1, and MEF2B in lung adenocarcinoma and normal lung tissues using TCGA data, and the analysis indicated that the three transcription factors were all downregulated in lung adenocarcinoma tissues." (PMID 40068093, 2025).
lymph node metastasis (1 paper, 2022). "The results show that the expression of IKZF1–3 mRNAs in SKCM significantly decreased with higher T-stage and significantly decreased when SKCM involved local lymph node metastasis that penetrated the original tissue boundary." (PMID 36353107, 2022).
monoclonal gammopathy of undetermined significance (1 paper, 2015). "In contrast, we did not observe significant change in the expression of either IKZF1 or IKZF3 genes during the progression from normal to monoclonal gammopathy of undetermined significance and SMM to newly diagnosed MM." (PMID 26430725, 2015).
monocytic leukemia (1 paper, 2023). "PTPN11mut was more common in myelomonocytic and monocytic leukemia, and was more likely to co‐mutate with KRAS, KMT2C, NRAS, U2AF1, NOTCH1, IKZF1, and USH2A mutations than PTPN11wt." (PMID 37937729, 2023).
multiple sclerosis (1 paper, 2022). A progressive autoimmune disorder affecting the central nervous system resulting in demyelination. "To demonstrate the usability of the tool, we designed a case study for multiple sclerosis that revealed IKZF1 as a promising hub regulator, which was supported by independent ChIP-seq data." (PMID 36699378, 2022).
Myelodysplasia (1 paper, 2023). Clonal hematopoietic stem cell disorders characterized by dysplasia (ineffective production) in one or more hematopoietic cell lineages, leading to anemia and cytopenia. "Among them, IKZF1 N159S was a recurrent hotspot mutation, which closely clustered in a subset of patients with myelodysplasia‐related mutations and upregulated gene expression of the HOXA/B family genes." (PMID 37345307, 2023).
neuroblastoma (1 paper, 2017). Neuroblastoma (NB) is the most common solid, extracranial childhood tumor. "Interestingly, several sequence alterations in other genes involved in chromatin regulation in neuroblastoma have been found, including EP300, CREBBP, TTF2, KDM5A, CHD9, and gene IKZF1, which might undergo somatic mutations and promote NB occurrence." (PMID 28055978, 2017).
Opportunistic infection (1 paper, 2021). An infection that is caused by a pathogen that would generally not be able to cause an infection in a host with a normal immune system. "Interestingly, AIOLOS N160S is the site homologous to IKAROS N159S, with patients carrying this particular IKZF1 mutation also displaying abnormal T and B cell phenotypes, opportunistic infections (i.e., PJP), and hematologic malignancy susceptibility." (PMID 34694366, 2021).
osteoarthritis (1 paper, 2018). A noninflammatory degenerative joint disease occurring chiefly in older persons, characterized by degeneration of the articular cartilage, hypertrophy of bone at the margins and changes in the synovial membrane. "IKZF1 participated in inflammation suggested that IKZF1 may contribute to osteoarthritis." (PMID 30086750, 2018).
periodontitis (1 paper, 2026). An acute or chronic inflammatory process that affects the tissues that surround and support the teeth. "In terms of the shared molecular mechanisms underlying periodontitis and renal cell carcinoma, six genes (IKZF1, LGALS1, LSP1, MNDA, VIM and WAS) were consistently upregulated in both disease tissues, indicating their potential involvement in the common pathogenesis of the two diseases." (PMID 42157182, 2026).